ZNF224 (zinc finger protein 224)
Diseases named in the same sentence as ZNF224 in open-access papers (continued):
Sharing a sentence is not in itself a finding about the gene and the disease.
dementia (1 paper, 2010). Loss of intellectual abilities interfering with an individual's social and occupational functions. "In contrast, similar to nearly all AD GWA studies performed to date, the initial reports of association with the PCK1 and ZNF224 loci come from AD cases recruited from a neurology clinic population with prevalent dementia." (PMID 20574532, 2010).
kidney cancer (1 paper, 2021). Primary or metastatic malignant neoplasm involving the kidney. "In our results, ZNF224 is negatively associated with cancer dedifferentiation—KIRC tumors that exhibit cancer stem cell-like phenotype express significantly lower levels of ZNF224, suggesting its tumor-suppressive role in kidney cancer." (PMID 34638319, 2021).
Lymphadenopathy (1 paper, 2022). Enlargement (swelling) of a lymph node. "Interestingly, we observed a significant increase in ZNF224 expression in patients with lymphadenopathy and both lymphadenopathy and splenomegaly." (PMID 36425656, 2022).
rectal cancer (1 paper, 2025). A primary or metastatic malignant neoplasm that affects the rectum. "Among the six relevant RMPs identified in rectal cancer patients, two—CHD4 and ZNF224—were specifically found to be involved in DNA repair and maintenance." (PMID 40149344, 2025).
tumor (8 papers, 2016 to 2025). "The pathogenic role of ZNF224 is cancer‐type specific and tumor context‐dependent, being able to act as an oncogene or a tumor suppressor in human cancers." (PMID 40321146, 2025). "Taken together, ZNF224 in CML acts as a tumor suppressor that is able to promote the expression of proapoptotic genes and repress the expression of antiapoptotic genes to enhance drug resistance." (PMID 33672287, 2021). "The Kruppel-like zinc-finger protein ZNF224 is a transcriptional repressor, which has been recently proposed to play a dual role in carcinogenesis, acting as a tumor suppressor or an oncogene, depending on molecular partners and cellular contest." (PMID 29423056, 2018). "miR-663a, identified as a target gene of ZNF224, exhibits a differential function in different cancer types, as a tumor suppressor or as an oncogene." (PMID 27105517, 2016). "Therefore, the role of ZNF224 seems quite relevant in orchestrating multiple oncogenic events for tumor initiation and progression." (PMID 40321146, 2025). "Interestingly, ZNF224 can perform different functions according to the difference in tumor microenvironment." (PMID 37370088, 2023). "However, ZNF224 is used as an oncogene in bladder cancer to promote the rapid growth of tumor cells and the resistance to tumor cell apoptosis." (PMID 37370088, 2023). "In detail, in chronic myeloid leukemia (CML), ZNF224 behaves as a tumor suppressor gene." (PMID 34684876, 2021). "In carcinogenesis, ZNF224 was assigned a dual role of a tumor suppressor and oncogene." (PMID 33672287, 2021). "Indeed, it was demonstrated that ZNF224 works as a tumor suppressor or as an oncogene in different types of cancer." (PMID 34684876, 2021). "We have learned, in these last few years, a great deal about the function of ZNF224 and other KRAB-ZFPs in the transcriptional regulation of target genes, but we still have much more to understand about their role in regulating cellular processes in normal and tumor cells." (PMID 34684876, 2021). "It is not surprising any more that ZNF224 functions as a tumor suppressor or oncogene in cancer because there is a possibility that the function of ZNF224 depends on co-activator or repressor bound to KRAB domain of ZNF224." (PMID 27105517, 2016).
cancer (6 papers, 2016 to 2025). A tumor composed of atypical neoplastic, often pleomorphic cells that invade other tissues. "In the present study, we thoroughly investigated the molecular mechanisms underlying the oncogenic role of ZNF224 in this kind of cancer." (PMID 40321146, 2025). "Therefore, in different types of cancers, ZNF224 may affect cell growth and proliferation in association with deregulated cofactors, such as PRMT5." (PMID 34684876, 2021). "To this aim, we quantified the activity of caspase 3/7 by using the Promega Caspase‐Glo 3/7 assay in conditions of ZNF224 overexpression and subsequent cisplatin treatment, a chemotherapeutic drug used for cancer therapy." (PMID 40321146, 2025). "The transcription factor ZNF224 has been shown to be involved in numerous pathways related to cell survival, cell death, and cell cycle in various human cancers through its interaction with different molecular partners." (PMID 40321146, 2025). "Global identification of ZNF224 target genes and interacting proteins will be required to improve understanding of its regulatory network in cancer." (PMID 36425656, 2022). "H&E and immunohistochemical staining showed that ZNF224 expression level was increased in cancer region compared to non-cancer region (15 of 18 cases), whereas ZNF224 mRNA expression was increased only in 8 cases of 18 cases." (PMID 27105517, 2016). "Indeed, it has been shown that ZNF224 can act as a repressor, an activator and a cofactor for other DNA-binding transcription factors in different human cancers." (PMID 34684876, 2021). "In this scenario, it is quite evident that the identification of novel protein partners of ZNF224 might lead to the complete knowledge of how ZNF224 can be regulated and to the discovery of new functions for this protein in proliferation, differentiation, cancer and metabolism." (PMID 34684876, 2021). "ZNF224 is a protein model providing numerous and interesting pieces of evidence that could be useful to integrate data from other laboratories and to define the mechanisms and pathways implied in the control of proliferation, differentiation, cancer and metabolism." (PMID 34684876, 2021). "Although other members of this family, such as ZNF224 and ZNF217, play important roles in cancer development, the role of ZNF286A has not been studied in any disease." (PMID 36134026, 2022).
ZNF224 also shares sentences with these, for which no sentence is quoted: acute myeloid leukemia (1 paper); bladder (1); childhood kidney cancer (1); hematological cancers (1); liver cancer (1); memory impairment (1); myeloma (1); Splenomegaly (1).